RNU6-557P (RNA, U6 small nuclear 557, pseudogene)
Gene: Small nuclear RNA gene on chromosome 3 (73,092,148 to 73,092,257, reverse strand). Ensembl gene ENSG00000252651.
Homologues: Orthologues: chimpanzee U6 (98% identical). Paralogues in human: RNU6-29P (73% identical), RNU6-38P (73% identical), RNU6-480P (73% identical), RNU6-1005P (72% identical), RNU6-1095P (72% identical), RNU6-1103P (72% identical), RNU6-151P (72% identical), RNU6-20P (72% identical), RNU6-21P (72% identical), RNU6-28P (72% identical), RNU6-616P (72% identical), RNU6-618P (72% identical), and 1285 more.